Y_RNA (Y RNA )
Gene: Miscellaneous RNA gene on chromosome 1 (248,594,925 to 248,595,033, reverse strand). Ensembl gene ENSG00000201602.
Homologues: Orthologues: guinea pig Y_RNA (81% identical), macaque Y_RNA (81% identical), dog Y_RNA (69% identical). Paralogues in human: RNY1 (88% identical), Y_RNA (85% identical), Y_RNA (84% identical), Y_RNA (83% identical), Y_RNA (82% identical), RNY1P11 (81% identical), RNY1P8 (81% identical), Y_RNA (81% identical), RNY1P2 (80% identical), Y_RNA (80% identical), Y_RNA (79% identical), RNY1P12 (78% identical), and 94 more.